NRP1 (neuropilin 1)
Diseases named in the same sentence as NRP1 in open-access papers (continued):
Sharing a sentence is not in itself a finding about the gene and the disease.
colorectal cancer (39 papers, 2010 to 2026). A primary or metastatic malignant neoplasm that affects the colon or rectum. "In colorectal cancer, NRP-1 overexpression is linked to greater invasiveness and reduced survival, while NRP-2 is associated with faster tumor growth." (PMID 40430075, 2025). "Here, we identify two human NRP1 splice variants resulting from the skipping of exon 4 and 5, respectively, in colorectal cancer (CRC)." (PMID 31420553, 2019). "In this study, we discover two human NRP1 splice variants from colorectal cancer (CRC) cell lines and tissue specimens." (PMID 31420553, 2019). "NRP1 expression was analyzed using immunohistochemistry in a consecutive cohort of 110 patients with stage III colorectal cancer who underwent curative surgery." (PMID 42166776, 2026). "Tumor cell and stromal NRP1 contributions were compared using NRP1-knockout colorectal cancer cell lines." (PMID 42166776, 2026). "In vivo experiments on zebrafish xenografts pertaining to the progression of colorectal cancer (CRC) through the miR-24-3p/NRP1 axis have predicted poor prognosis." (PMID 40277760, 2025). "NRP-1 is overexpressed in different malignancies, including gastric, liver, and colorectal cancer, correlating with tumor stage, metastasis, and invasion." (PMID 40430075, 2025). "When co-cultured with tumor tissue from human colorectal cancer liver metastases, these macrophages showed induced NRP1 expression." (PMID 40134439, 2025). "Differential Expression: RNA sequencing (RNA-seq) studies have shown that NRP1 is often upregulated in various cancers, including breast, prostate, and colorectal cancers." (PMID 40277760, 2025). "Patients with colorectal cancer (CRC) who express both NRP1 and NRP-2 have a worse prognosis than those who express either one neuropilin or none at all." (PMID 35052853, 2022). "In accordance with the expression profile observed in normal tissues, NRP1 was also highly expressed in ovarian cancer, colorectal cancer, and kidney cancer." (PMID 36338984, 2022). "It was reported that CYTOR positively regulated NRP1 expression by sponging with miRNA-206 in colorectal cancer, and miRNA-206 was significantly increased in human OA chondrocytes." (PMID 33749514, 2021). "Recently, a study has shown that aberrant expression of CDC42 in colorectal cancer can cause the migration, invasion, and metastasis through activation of the VEGF/NRP1 axis and is closely related to the prognosis of the patients." (PMID 34291059, 2021). "LncRNA 00152 functions as a ceRNA to regulate NRP1 expression by sponging miRNA-206 in colorectal cancer." (PMID 32228518, 2020). "We investigated nanobodies (Nbs) targeting neuropilin-1 for their potential to hamper colorectal carcinoma development in mice." (PMID 33266104, 2020). "In colorectal cancer, miR-206 inhibits tumor growth and invasion by downregulating the long non-coding RNA lnc00152 which again promotes NRP1 expression and EMT." (PMID 30717262, 2019). "In colorectal cancer metastasis, for example, miR320b abolishes downregulation of NRP1, β-catenin, and Rac-1 by competing with miR320a." (PMID 30717262, 2019). "NRP1 expression is also found on peripheral blood mononuclear cells in vitro cultured in presence of colorectal cancer tissue." (PMID 29067024, 2017). "Previous studies have suggested that NRP-1 expression correlates with tumour growth and invasiveness in colorectal cancer and that there is an increase in both intensity and area of expression from low-grade to high-grade dysplasia in colorectal adenomas." (PMID 21401950, 2011). "As NRP-1 is involved in both angiogenesis and the prevention of apoptosis in colorectal cancer these data suggest two potential mechanisms for chemoprevention - through the apoptotic regulatory function of NRP-1 and through its pro-angiogenic role." (PMID 20950431, 2010).
colorectal cancer (continued). "In pathologic specimens from patients with colorectal cancer, widespread NRP1 expression was noted across tumor cells, the stromal compartment, and the vasculature, suggesting potential applicability of iRGD-based therapy in human colorectal cancer." (PMID 42166776, 2026). "Similarly, PBMCs isolated from colorectal cancer patients exhibited low NRP1 expression compared to TILs." (PMID 40134439, 2025). "In addition, the expression levels of neuropilin 1 and neuropilin 2, receptors for Sema3A, and Neogenin and deleted in colorectal cancer (DCC), receptors for Netrin-1, were evaluated by RT-qPCR." (PMID 36986209, 2023). "In colorectal cancer, inhibition of NRP1 was able to inhibit metastasis of colorectal cancer cells." (PMID 36389678, 2022). "Also, VEGF operating through VEGFR2 and neuropilin-1 (NRP-1) induced both the number and function of intratumoral Tregs in colorectal cancer." (PMID 33996630, 2021). "Our data suggest that targeting neuropilin-1 in cancer using neuropilin-1 blocking Nbs delays tumor growth and extends the survival through a shift in the anti-tumor macrophage/pro-tumor macrophage ratio and activation of colorectal cancer-specific CD8+ T cells." (PMID 33266104, 2020). "More importantly, NRP-1 expression associates with the advanced stage of disease, and negatively correlates with the prognosis of hepatocellular carcinoma, colorectal cancer, and esophagus squamous cell carcinoma, indicating that NRP-1 is a potential molecular target for cancer therapy." (PMID 26795388, 2016). "NRPl overexpression is positively associated with metastatic potential, advanced stage, shorter 5-year survival rate and/or clinical grade in prostate, gastrointestinal and colorectal carcinoma, suggesting a protumorigenic role of NRP1 and direct contribution of NRP1 to tumor progression." (PMID 24926961, 2014). "Here, the authors show that defects in N-glycosylation of two neuropilin-1 splice variants enhance the co-internalisation of Met, it’s interaction with β1-integrin, and subsequent constitutive activation of FAK/p130Cas signalling in endosomes to promote colorectal cancer metastasis." (PMID 31420553, 2019). "Numerous analyses have shown that enhanced expression of NRP-1 and NRP-2 in colorectal cancer tissues correlates with adverse patient prognosis, including a higher risk of metastasis and shorter overall survival." (PMID 40430075, 2025). "NRP1 protein was highly expressed in ovarian cancer and colorectal cancer in the HPA030278 dataset, and was also highly expressed in colorectal cancer in the CAB004511 dataset." (PMID 36338984, 2022). "Butyrate diminishes the recruitment of Sp1 to the NRP1 promoter in colorectal cancer, whereas the effect of TSA on NRP1 expression in endothelial cells is mediated by semaphorine III." (PMID 34635175, 2021). "NRP1 recently attracted attention as a novel co-receptor for SARS-CoV-2 in two separate studies that used Hela, HEK293T and the colorectal cancer cell line Caco-213,14." (PMID 34535662, 2021). "Further, the group also detected NRP1+ Tregs in the peripheral blood isolated from patients suffering from pancreatic ductal adenocarcinoma (PDAC) and colorectal cancer liver metastasis." (PMID 29067024, 2017). "Here we demonstrate that butyrate down-regulates NRP-1 and VEGF at the mRNA and protein level in colorectal cancer cell lines." (PMID 20950431, 2010). "Notably, neuropilin-1 (NRP-1) and neuropilin-2 (NRP-2) have been identified as significant regulators of the tumor microenvironment in colorectal cancer (CRC)." (PMID 40430075, 2025). "Moreover, two different studies with human colorectal cancer (CRC) cells showed that after adaptation to sunitinib, CRC cells switched from a VEGFR-dependent to a NRP1/cMet-dependent pathway promoting treatment evasion, and that targeting NRP1 suppressed migration activation." (PMID 36376373, 2023).
colorectal cancer (continued). "Nanobodies (Nbs) targeting NRP-1 were generated for their potential to hamper the NRP-1/Sema3A interaction and their impact on colorectal carcinoma (CRC) development was evaluated in vivo through the generation of anti-NRP-1-producing CRC cells." (PMID 33266104, 2020).
hepatocellular carcinoma (32 papers, 2007 to 2025). A malignant tumor that arises from hepatocytes. "Serum angiogenetic markere neuropilin-1 (NRP-1) combinated with AFP can enhance the diagnostic power in hepatocellular carcinoma, and predicted the poor prognosis." (PMID 34991620, 2022). "Ghafar investigated serum NRP-1 levels in patients with hepatocellular carcinoma and evaluated the diagnostic value of NRP-1 as a serological marker." (PMID 35115027, 2022). "Other studies have shown that NRP-1 enhances angiogenesis in HSECs during liver fibrosis as a co-receptor of VEGFR2 and that hepatocyte NRP-1 promotes the proliferation and migration of hepatocellular carcinoma." (PMID 40419692, 2025). "In both a human study of NSCLC and a murine model of hepatocellular carcinoma, small interfering RNA (siRNA)-mediated knockdown of NRP1 reduced the invasiveness of cancer cells in vitro." (PMID 40277760, 2025). "NRP1 is related to axonal activation, angiogenesis, and the increased level of NRP1 in the hepatocyte is related to hepatocellular carcinoma." (PMID 36077090, 2022). "TEA domain transcription factor (TEAD) binding motif is also present in the promoter region of NRP1, and the expression of NRP1 is regulated by TEAD in hepatocellular carcinoma (HCC)." (PMID 35600336, 2022). "Serum NRP-1 and ANG-2 levels have been used as markers of hepatocellular carcinoma as their high levels are associated with advanced tumor characteristics." (PMID 35918714, 2022). "NRP1, a transmembrane co-receptor for semaphorins and heparin-binding pro-angiogenic cytokines, has been reported to be upregulated in hepatocellular carcinoma, as it contributes to tumor growth and vascular remodeling." (PMID 35707353, 2022). "NRP1 is overexpressed in numerous human tumor tissues, including breast, lung, colorectal, and hepatocellular cancer." (PMID 34249735, 2021). "MiR-148b was reported to inhibiting NRP1 and regulating cancer stem cells in hepatocellular carcinoma." (PMID 32508529, 2020). "Experimental proof of the enhanced anti-hepatoma effect of SSd in combination with NRP-1 knockdown was provided for the first time." (PMID 30978940, 2019). "NRP-1 has been reported to display higher expression in hepatocellular carcinoma cell lines than in normal hepatic cell lines." (PMID 30978940, 2019). "Out metabolomic studies indicated that the enhanced anti-hepatoma effect of NRP-1 knockdown, in combination with SSd, mainly influenced the lipid metabolism, but this should be validated in the future." (PMID 30978940, 2019). "Further metabolic pathway analysis revealed that disturbed lipid transportation and phospholipid metabolism probably contributed to the enhanced anti-hepatoma effect by NRP-1 knockdown in combination with SSd." (PMID 30978940, 2019). "In order to select the most suitable cell lines, we compared NRP-1 expression levels in hepatocellular carcinoma cell lines HepG2 and SMMC-7721 and a normal hepatic cell line L-02 by Western blot." (PMID 30978940, 2019). "Our study provided evidence of the enhanced anti-hepatoma effect of SSd on hepatocellular carcinoma cells with NRP-1 knockdown." (PMID 30978940, 2019). "In addition, serum neuropilin-1 and angiopoietin-2 are potential markers for hepatocellular carcinoma diagnosis." (PMID 34656128, 2021). "The results suggested that NRP-1 knockdown could significantly enhance the anti-hepatoma effect of SSd." (PMID 30978940, 2019). "Therefore, it was speculated that the anti-hepatoma effect of SSd might be enhanced if we could downregulate NRP-1." (PMID 30978940, 2019). "In our study, four annotated differential metabolites related to both NRP-1 knockdown and SSd treatment were observed to have the same trend during an intervention, which suggested that the combined action of those metabolites contributed to the advanced anti-hepatoma effect." (PMID 30978940, 2019). "In hepatocellular carcinoma (HCC), Treg’s infiltration is mediated by NRP-1, a co-receptor of VEGFRs." (PMID 34064508, 2021).
hepatocellular carcinoma (continued). "Sema3C has recently been studied as a novel biomarker in Hepatocellular carcinoma (HCC), where NRP1 and Integrin Beta1 (ITGβ1) act as functional receptors of Sema3C which activates Serine threonine Kinase (AKT)/GLI Family Zinc Finger 1 (Gli1)/c-Myc signaling pathways leading to tumor initiation." (PMID 40277760, 2025). "Expression of NRP1 is found in hepatocellular carcinoma (HCC) but not in normal hepatocytes." (PMID 37894289, 2023). "This leads us to ask whether NRP-1 knockdown would enhance the damage effect of SSd at 7.5 μM, due to the upregulated NRP-1 and unexpected side effects appearing simultaneously with the anti-hepatoma effect of SSd." (PMID 30978940, 2019).
colon carcinoma (31 papers, 2010 to 2025). "NRP‐1 expression has been associated with prognosis in a variety of tumours, such as liver cancer, bladder cancer and colon cancer." (PMID 32951327, 2020). "In colon cancer, elevated NRP1 expression is associated with a less severe prognosis, and, at least in PANC-1 pancreas adenocarcinoma cells, NRP acts as a tumor suppressor." (PMID 30717262, 2019). "NRP-1 has been implicated as an anti-apoptotic protein in colon cancers in addition to its role in angiogenesis, which is reinforced by its staining pattern not being limited to obvious microvessels." (PMID 21401950, 2011). "We found that the AD in 14.2 exons of NRP1 was associated with overall survival in colon cancer." (PMID 31586988, 2019). "In colon cancer, tumor expression of NRP1 is associated with a better prognosis." (PMID 30027561, 2018). "NRP-1 has been linked to cancer progression and aggressiveness in colon tumours." (PMID 21401950, 2011). "NRP1 is a membrane-bound coreceptor to a tyrosine kinase receptor, and it contributes to colon cancer angiogenesis and growth." (PMID 39758846, 2024). "Overexpression of NRP1 leads to increased tumor growth and angiogenesis in human colon cancer cells xenografted into nude mice." (PMID 37894289, 2023). "We found that relative NRP1 mRNA expression level was significantly lower in both the human lung adenocarcinoma cell line PC-9 and four human colon cancer cell lines compared with normal human cell lines." (PMID 36338984, 2022). "We found that NRP-1 was highly expressed in colon cancer tissues and cell lines, enabling the iRGD-Exos to be effectively ingested by colon cancer cells." (PMID 34616773, 2021). "The modified exosomes showed high binding ability to NRP-1-positive colon cancer cells and significantly inhibited tumor growth in vitro and in vivo." (PMID 34616773, 2021). "The sw480‐lohp/HCT116‐lohp cells, oxaliplatin‐resistant colon cancer cell lines, showed a higher level of expression of αvβ3 and NRP‐1 than the normal colon cell line ncm460." (PMID 34213835, 2021). "Serum sample 30# was from a colon cancer patient, and the serum concentrations of Nrp1 and Nrp2 were 15 000 and 9956 pg/mL, which were 22.4‐ and 21.5‐fold the mean values for serum from normal human samples." (PMID 30758083, 2019). "Butyrate also down-regulates the key apoptotic and angiogenesis regulator neuropilin-1 (NRP-1) to inhibit tumor cell migration and survival in colon cancer." (PMID 23593331, 2013). "Our recent data show that the transmembrane glycoprotein neuropilin-1 (NRP-1) is downregulated by butyrate in several colon cancer cell lines." (PMID 21401950, 2011). "NRP-1 is up-regulated not only in vessels within adenomas and carcinomas, but also in hyperplastic adenoma cells and invasive colon cancer compared to normal mucosa." (PMID 21401950, 2011). "NRP-1 is expressed in morphologically normal colonic epithelium and is commonly over-expressed in human colon cancer where it correlates with advanced grade, metastatic potential, and decreased patient survival." (PMID 20950431, 2010). "The interplay between the virus and the colon cancer cells is guided by the presence of the complex ACE2/NRP-1, allowing an effortless infection to take place and ultimately leading to a direct immune response and the destruction of the tumor cells by cytotoxic T cells." (PMID 36768649, 2023). "Regulation of NRP1 levels in colon cancer cells may involve epidermal growth factor (EGF) and MAPK signaling." (PMID 37894289, 2023). "Moreover, conditioned medium from NRP1-transfected colon cancer cells enhances endothelial cell migration." (PMID 37894289, 2023). "Moreover, NRP-1 can promote the migration and survival of colon cancer cells in response to vascular endothelial growth factor (VEGF) binding." (PMID 33510943, 2021).
colon carcinoma (continued). "NRP-1 is reported to be up-regulated in cells of several cancers such as glioma, prostate carcinoma, breast cancer, gastric cancer, pancreatic carcinoma, colon cancer and acute myeloid leukemia." (PMID 24053763, 2013). "We have shown that NRP-1 is down-regulated by butyrate in colon cancer cell lines in vitro and we hypothesized that butyrate produced in the lumen would have an analogous effect on the colon mucosa in vivo." (PMID 21401950, 2011). "However, as yet it is not clear which of these elements is involved in the up-regulation of NRP-1 expression in colon cancer." (PMID 20950431, 2010). "In this study, we successfully established and identified iRGD‐modified exosomes (iRGD‐exosome), and it was confirmed that both αvβ3 and NRP‐1 were highly expressed in colon cancer and cell lines, which demonstrated that colon cancer could be a potential target for iRGD‐exosome." (PMID 34213835, 2021). "The overexpression of NRP-1 has been shown to regulate not only angiogenesis, but also other aspects of tumorigenesis, such as modulation of apoptosis and cell migration in human colon cancer, epithelial-mesenchymal transition of human ovarian cancer, and especially tumour-induced immune tolerance." (PMID 25873749, 2015). "Our recent data show that butyrate, a product of fibre fermentation in the colon lumen, downregulates NRP-1 expression in colon cancer cell lines and we hypothesized that butyrate, and potentially other SCFA, produced in the lumen would have an analogous effect on the colon mucosa in vivo." (PMID 21401950, 2011). "Therefore, modification of Sp family activity by butyrate and the potential of NRP-1 as an Sp1 target led us to investigate the ability of butyrate to modulate NRP-1 expression, with a view to providing an alternative therapy or chemopreventive strategy for colon cancer." (PMID 20950431, 2010). "Patient data indicate that colorectal tumours with increased NRP-1 expression have a greater incidence of metastases, increased proliferation index and reduced numbers of apoptotic cancer cells than tumours with low NRP-1 staining suggesting that NRP-1 may protect colon cancer cells from apoptosis." (PMID 20950431, 2010). "Neuropilin-1 (NRP-1) has been shown to promote tumour cell migration and survival in colon cancer in response to VEGF binding." (PMID 20950431, 2010). "More recently NRP-1 has been shown to be expressed in colon cancer and inhibition of NRP-1 in colon cancer cell lines using siRNA significantly increased cancer cell apoptosis." (PMID 20950431, 2010). "Quantitative PCR and flow analysis were performed, and the results showed that NRP-1 was highly expressed in the colon cancer cells Caco2 and HCT116, rather than the 293T cells." (PMID 34616773, 2021). "CD8+ TIL isolated from engrafted lung tumour cell lines LL2 and TC-1, and the colon cancer cell line MC-38 also expressed high levels of Nrp-1, as opposed to spleens and TdLN." (PMID 31350404, 2019). "To identify whether colon cancer was the preferred target, we chose 13 paired cancerous and noncancerous tissues to assess the expression of αvβ3 and NRP‐1." (PMID 34213835, 2021).